CHI3L1 (chitinase 3 like 1)
Diseases named in the same sentence as CHI3L1 in open-access papers (continued):
Sharing a sentence is not in itself a finding about the gene and the disease.
tumor (continued). "Galectin 3 (Gal3) binding to CHI3L1 activates the AKT/mTOR-mediated transcriptional regulatory network (NF-κB and CEBPβ), leading to an immune suppression and polarization of M2 TAMs, which then activate PD-1 and CTLA-4 to promote tumor progression." (PMID 37759870, 2023). "Chitinase-3 like-protein-1 (CHI3L1) is a member of the glycoside hydrolase family 18, which is synthesized and secreted by a variety of cells, including some inflammatory cells, connective tissue cells, and tumor cells." (PMID 37091145, 2023). "Recently it has been demonstrated that chitinase-3-like 1 (CHI3L1), a protein complex upregulated in GBM, increases immunosuppression within the tumor microenvironment by increasing infiltration of MDMs and MG while additionally supporting TAM immunosuppression and subsequent residence to therapies." (PMID 37275361, 2023). "In addition, CHI3L1 protects cancer cells from apoptosis by remodeling the extracellular matrix (ECM), thereby creating a suitable substrate for tumor growth and progression." (PMID 37887529, 2023). "Our examination of the dataset revealed that CHI3L1 expression levels were notably higher in tumour tissues compared with noncancerous tissues and to corresponding matched normal tissues." (PMID 37902124, 2023). "To identify candidate stroma-derived factors that might influence desmoid tumor cell proliferation, we treated mutant-only cultures with recombinant IGFBP3, PTX3, CCL2, CXCL12, and CHI3L1 in serum-free conditions." (PMID 37377751, 2023). "Most importantly, there is a proposition that CHI3L1, compared with the widely used PSA, could provide more informative insights into predicting tumour burdens and the potential for metastasis." (PMID 37902124, 2023). "In addition, secreted CHI3L1 binds to the receptor on cancer cells and macrophages to activate AKT, β-catenin and NF-κB signaling pathways to promote tumor growth and metastasis." (PMID 34987649, 2022). "Multiplex IF-IHC of Rab37, CHI3L1 and CD163 was performed on 23 tumor specimens." (PMID 34987649, 2022). "We further demonstrated that the effects of CHI3L1 are tumor independent, at least in part, because transgenic overexpression of CHI3L1, in the absence of tumor, reproduced these events." (PMID 36618349, 2022). "Strikingly, the protein complex formed by CHI3L1-Gal3 promotes the infiltration of “pro-tumour” M2 but not “anti-tumour” M1 macrophages and appears to be regulated transcriptionally by NF-κB/CEBPβ in the CHI3L1/Gal3/PI3K/Akt/mTOR axis." (PMID 36555253, 2022). "In sum, these studies highlight that bispecific antibodies that simultaneously target CHI3L1 and CTLA-4 have prominent additive or synergistic anti-tumor effects in vivo and in vitro via its ability to induce CD8+ cytotoxic T cells and enhance tumor cell expression of PTEN." (PMID 36618349, 2022). "Furthermore, the simultaneous targeting of CHI3L1 and the programmed cell death of protein-1/programmed death ligand-1 axis promoted cytotoxicity of CD8+ T cells and tumor cell death." (PMID 35335885, 2022). "This study also revealed new immune suppressive miR-200c targets that may dampen anti-tumor immunity in mTNBC, including tryptophan-2,3 dioxygenase (TDO2), chitinase-3 like-1 (CHI3L1) and heme oygenase-1 (HO-1)." (PMID 34832904, 2021). "Also, the positive correlation between Chitinase 3-like 1 and IL8 (0.57) or MMP2 (0.50) suggest a role in tumor growth and metastasis pathways." (PMID 33846436, 2021). "Moreover, LGG tumors with CD302 or FABP5 overexpression highly expressed some oncogenes, including GPR65, PIK3CG, CHI3L1, and RAB36, which were reported to promote tumor growth and metastasis." (PMID 32775301, 2020). "CHI3L1 is actually present in the secretomes from all three MDM subtypes, albeit with elevated levels for m1-MDM, which, however, does not preclude a contribution of CHI3L1 to tumor cell migration as seen in other studies." (PMID 32312959, 2020).
tumor (continued). "In serum, on the other hand, CHI3L1 and LCN2 were significantly increased at 1, 3, and 6 w p.i. in the 4T1- compared to the Py230-based intraductal model, reflecting the enhanced metastatic progression of 4T1 tumor cells following intraductal inoculation." (PMID 31921184, 2019). "CHI3L1 and LCN2 levels in spleens corroborated the increased splenomegaly at 3 and 6 w p.i. in the 4T1- compared to the Py230-based intraductal model and further indicated the presence of enhanced leukocyte reactions in the 4T1 tumor-bearing mice." (PMID 31921184, 2019). "To determine whether the CHI3L1/CD44 axis governs GC cell metastasis in vivo, we evaluated experimental lung metastasis after lateral tail vein injection of tumor cells." (PMID 30165890, 2018). "Collectively, this study demonstrates Chi3l1 is a regulator of Th1 and CTL which could be a therapeutic target to enhance anti-tumor immunity." (PMID 29403003, 2018). "Such recruitment of macrophages by the CHI3L1-positive CTCs may induce M2-type local immunosuppression and protect the disseminated SCLC tumor cells from attack by the immune system." (PMID 26425658, 2015). "The role of hematopoietic versus non-hematopoietic cell-derived CHI3L1 in tumor formation was next examined using the AOM/DSS-treated BM-chimeric mice (Brp39 KO BM-> WT and WT BM -> Brp39 KO)." (PMID 26431492, 2015). "Lung tissue sections from doxycycline-untreated mice, -treated without tumor, and -treated with tumor mice were immunohistochemically stained with anti-CHI3L1 antibody." (PMID 23613996, 2013). "Doxycycline-treated mice without tumor (42.1±67.9 ng/ml, p = 0.043) also showed the increased CHI3L1 concentration compared with doxycycline-untreated mice." (PMID 23613996, 2013). "ROC analysis indicated impressive capability of CHI3L1 concentration in discriminating the tumor group with the non-tumor group and the doxycycline-untreated group." (PMID 23613996, 2013). "Our data show that the overexpression of CHI3L1 alone is sufficient to make 293 cells tumorigenic in Wistar rat brain, whereas no tumor was observed in animals injected with empty vector-transfected 293 cells." (PMID 23675241, 2011). "A study has found that CHI3L1 could activate various signaling pathways, including protein kinase B (AKT), β-catenin, and nuclear factor kappa B (NF-κB), and increase the number of regulatory T cells, stimulating the tumor microenvironment." (PMID 40821115, 2025). "Chitinase 3-like protein 1 (CHI3L1), also known as YKL-40 in humans, is a secreted glycoprotein with multiple functions that is expressed in various cell types, including endothelial cells, activated macrophages, chondrocytes, neutrophils, fibroblasts, synovial and various tumor cells." (PMID 40044787, 2025). "CHI3L1 has been reported to stimulate the proliferation of fibroblasts, synovial cells, and chondrocytes by modulating chemokine and MMP expression under inflammatory conditions, suggesting its role in the recruitment of stromal cells into the tumor microenvironment." (PMID 40643503, 2025). "Additionally, CHI3L1 affects MMP9, promoting tumor invasion and metastasis." (PMID 38177294, 2024). "Bispecific antibodies that target CHI3L1 and PD-1 can effectively enhance the activity of CD8 cytotoxic T cells in the tumor microenvironment and induce the expression of the tumor suppressor gene PTEN in tumor cells, thereby playing a synergistic antitumor effect." (PMID 39068486, 2024). "ELISA showed significantly increased CHI3L1 and CHI3L3 levels in the Ly6G+ compared to the Ly6G− fraction from untreated primary tumors, and CHI3L1 levels significantly decreased in both the Ly6G+ and even the low CHI3L1-expressing Ly6G− primary tumor fraction upon chitin treatment." (PMID 38605414, 2024). "Additionally, CHI3L1 affects MMP-9, contributing to tumor invasion." (PMID 38177294, 2024).
tumor (continued). "In addition, CHI3L1 expression displayed a negative correlation with tumor purity (Rho = −0.552, p = 8.01 × 10−31) but a significant positive correlation with neutrophil infiltration (Rho = 0.337, p = 3.26 × 10−11)." (PMID 37958973, 2023). "Cancer-associated fibroblasts (CAFs) can recruit adaptive and innate immune cells to the tumor microenvironment by producing chemokines and cytokines, such as CC-chemokine ligand (CCL) 2, CCL5, CXC-chemokine ligand (CXCL) 8, CXCL12, chitinase 3-like protein 1 (CHI3L1) and IL-6." (PMID 34465885, 2022). "Importantly, the relationship between Rab37 and CHI3L1 expression has never been examined in infiltrating immune cells in tumor tissue." (PMID 34987649, 2022). "Here, we reveal novel findings that Rab37 mediates CHI3L1 secretion in T cells and macrophages, the major constituent cells in TME, to promote M2 macrophage polarization and higher FOXP3+ Tregs to CD8+ T cells ratio in the tumor region, ultimately establishing an immunosuppressive TME." (PMID 34987649, 2022). "However, no significant changes of CHI3L1 expression was observed in tumors with different N stages, response to treatment and tumor residues." (PMID 34612767, 2021). "Gene expression analysis of purified astrocytes from both the tumor core and non-infiltrated cortex reveals a tumor-related up-regulation of Chitinase 3-like 1 (CHI3L1), a cytokine which is related to inflammation, extracellular tissue remodeling, and fibrosis." (PMID 31561550, 2019). "However, we did not observe significant functional differences in Chi3l1 KO NK cells compared to WT NK cells in tumor-killing activity or effector molecule expression in vitro and in vivo." (PMID 29403003, 2018). "Furthermore, the tumour volumes for shKLRC3 as well for shCHI3L1 grafts (50 mm3) were significantly reduced compared to shPRUNE2 grafts (150 mm3) suggesting that KLRC3 and CHI3L1 might be of prime importance in tumourigenesis process." (PMID 27641066, 2017). "However, the mechanisms that Chi3l1 uses to contribute to tumor progression have not been adequately defined." (PMID 27198666, 2016). "However we still cannot completely deny a possibility that the drop in S100A9 is just a consequence of tissue destruction/tumor progression and can decrease irrespective of CHI3L1." (PMID 26431492, 2015). "This may explain why the CHI3L1 concentration was higher in both BALF and blood of tumor mice." (PMID 23613996, 2013). "Neither anti-CHI3L1 nor chitin treatment affected hematogenous metastases to the lungs, but both treatment strategies equally and significantly decreased axillary lymph node metastases in 4T1 tumor-bearing mice, despite their differential effect on 4T1 primary tumor growth." (PMID 38605414, 2024). "However, chitinase-like proteins, including CHI3L1, CHI3L2 and SI-CLP (stabilin-1 interacting chitinase-like protein), have biological functions that contribute to stimulation of cell proliferation, support of angiogenesis and tumor invasion, cell interactions and immunomodulation." (PMID 39557919, 2024). "In our snRNA-Seq data of patient samples CHI3L1 expression was high in the high connectivity score-associated MES1 and AC tumor cell populations, but low in low connectivity score-associated NPC1 and OPC tumor cell populations as well as non-malignant cell types." (PMID 38320988, 2024). "However, the mechanism(s) by which CHI3L1 contributes to tumor development and progression have not been fully defined and the degree to which CHI3L1 contributes to its tumorigenic effects via activating T cell co-stimulators or the CTLA-4-B7 axis have not been investigated." (PMID 36618349, 2022). "CHI3L1 and CHI3L3 levels were highest in the CD45+ fraction of 4T1 primary tumors, identifying immune rather than tumor cells as major producers of both CLPs in the TME." (PMID 38605414, 2024).
tumor (continued). "We found the simultaneous high expression of CHI3L1 and CD206 were positively correlated with the tumor grade and was not co-localized within the GBM tissues." (PMID 36276655, 2022). "CHI3L1 levels (ng/mL) predict transfer to ICU or death independent of HTN, COPD, CAD, DM, active neoplasia, CKD, NLR at admission, hospitalization, length of stay in hospital, steroid therapy and LMWH administration during hospitalization." (PMID 35534648, 2022). "YKL-40, also known as non-enzymatic chitinase-3 like-protein-1 (CHI3L1), is a glycoprotein expressed and secreted mainly by inflammatory cells and tumor cells." (PMID 34432260, 2021). "Addition of TGF-β to tumor cell-N-MSC co-culture augmented MX2, BST2 and IL6 (right columns) but not ADAMTS12, LOXL2 GREM1 or CHI3L1 expression in N-MSCs." (PMID 29503225, 2018). "In our studies, we observed that CHI3L1, but not IL13, mediated IL‐13Rα2 activation which promoted tumor invasiveness, suggesting that these two ligands might promote differential signaling through IL‐13Rα2." (PMID 30094958, 2018). "Immunohistochemistry and western blotting analyses showed reduced protein expression of CHI3L1, PCNA, cyclin D1, Cdk 6, and MMP‐9, but the expression of cleaved caspase‐3 was increased; however, IL‐13Rα1 and IL‐13Rα2 levels were not changed in K284‐treated lung metastasis tumor tissues." (PMID 34758182, 2022).
cancer (295 papers, 2007 to 2026). A tumor composed of atypical neoplastic, often pleomorphic cells that invade other tissues. "Special emphasis is placed on the role of CHI3L1 in epithelial dysplasia and cancer, with a focus on its potential as a diagnostic biomarker and therapeutic target." (PMID 40643503, 2025). "Among the molecules implicated in inflammation-associated tumorigenesis, Chitinase 3-like 1 (CHI3L1/YKL-40/Brp-39) has emerged as a particularly compelling target due to its multifaced roles in immune regulation, tissue remodeling, and cancer progression." (PMID 40643503, 2025). "Studies using transgenic and knockout mouse models have revealed a strong association between CHI3L1 expression and cancer progression." (PMID 40643503, 2025). "Considering that CHI3L1 has numerous receptors and participates in complex signaling, increased research is required to identify effective inhibitory pathways and provide reliable data against CHI3L1-driven inflammation-associated cancers." (PMID 39068486, 2024). "The upregulation of CHI3L1 in the body is associated with various types of cancer, and the interplay between CHI3L1 and other inflammatory factors is an active research area." (PMID 39068486, 2024). "In contrast, the top downregulated gene in the LoGI group was CHI3L1, which is associated with cancer cell proliferation, invasion, metastasis, and angiogenesis and is highly expressed in metastatic PC." (PMID 38082056, 2024). "CHI3L1 plays similar roles in processes associated with the development of chronic inflammation and cancer." (PMID 39068486, 2024). "We also reported that CHI3L1 on CECs is further upregulated during the processes of colitis-associated cancer." (PMID 38667293, 2024). "In fact, pentoxifylline is described as a CHI3L1 inhibitor, and overexpression of CHI3L1 has been associated with poor survival in different types of cancer." (PMID 38835347, 2024). "In many types of cancer, the level of CHI3L1 is related to disease progression and prognosis, with overexpression of CHI3L1 generally associated with poor outcomes." (PMID 38003338, 2023). "Early detection of cancer can significantly improve treatment outcomes and patient survival rates, while using CHI3L1 alone as a diagnostic marker for early detection of CRC is not accurate." (PMID 38003338, 2023). "Further bioinformatics predictions using the cancer genome analysis (TCGA) supported this notion and revealed excessively expressed CHI3L1 and FN1 are associated with low OS in PDAC patients and high abundance of TAMs." (PMID 37444617, 2023). "Several reports highlighted a substantial correlation between CHI3L1 genetic variants and the risk, clinicopathologic progression and prognosis of various cancer types." (PMID 37902124, 2023). "Anti‐Chi3L1 antibody significantly decreased the expression of cancer growth and migration‐associated proteins, such as PCNA, cyclin D1, cyclin E, Cdk2, Cdk4, Cdk5, MMP2 and MMP9 in A549 lung metastasis model tissues." (PMID 34861103, 2022). "The role of CHI3L1 was studied in several chronic inflammatory diseases and cancers; our study extends these findings, demonstrating an association between CHI3L1 and poor virologic control in pediatric HIV infection." (PMID 36560606, 2022). "CHI3L1 is a protumor secretion protein and is associated with several signal pathways in the process of cancer development." (PMID 34987649, 2022). "Previous research suggested that CHI3L1 is associated with chemotaxis and migration of endothelial cells, smooth muscle cells and cancer cells." (PMID 33920100, 2021). "Increased CHI3L1 expression appears to be an important hallmark of inflammation and cancer and has been frequently observed in patients with poor prognosis." (PMID 26431492, 2015). "Chitinase-like glycoprotein CHI3L1 has been investigated extensively with respect to its expression patterns and possible association with inflammation and cancer." (PMID 23675241, 2011).